RPL17 (ribosomal protein L17)
Description:
Component of the large ribosomal subunit. The ribosome is a large ribonucleoprotein complex responsible for the synthesis of proteins in the cell.
Synonyms: rpL23; L17; uL22; DBA22; PD-1
Tractability: Small molecule: an approved drug acts on it; a structure with a bound ligand is known; a high-quality ligand is known. PROTAC: ubiquitination databases record sites on it; its protein half-life has been measured; a small molecule that binds it is known. Other modalities: a drug acting on it is in phase 2 or 3 trials.
Target class: Other cytosolic protein
Gene: Protein-coding gene on chromosome 18 (49,488,346 to 49,492,564, reverse strand). Ensembl gene ENSG00000265681.
Subcellular location: Cytoplasm
Subcellular location (Human Protein Atlas): Cytosol; Endoplasmic reticulum
Pathways (Reactome):
Metabolism of proteins: Eukaryotic Translation Termination; Formation of a pool of free 40S subunits; GTP hydrolysis and joining of the 60S ribosomal subunit; L13a-mediated translational silencing of Ceruloplasmin expression; PELO:HBS1L and ABCE1 dissociate a ribosome on a non-stop mRNA; Peptide chain elongation; Ribosome Quality Control (RQC) complex extracts and degrades nascent peptide; SRP-dependent cotranslational protein targeting to membrane; ZNF598 and the Ribosome-associated Quality Trigger (RQT) complex dissociate a ribosome stalled on a no-go mRNA
Metabolism of RNA: Major pathway of rRNA processing in the nucleolus and cytosol; Nonsense Mediated Decay (NMD) enhanced by the Exon Junction Complex (EJC); Nonsense Mediated Decay (NMD) independent of the Exon Junction Complex (EJC)
Cellular responses to stimuli: Response of EIF2AK4 (GCN2) to amino acid deficiency
Developmental Biology: Regulation of expression of SLITs and ROBOs
Disease: Viral mRNA Translation
Metabolism: Selenocysteine synthesis
Gene Ontology:
Molecular function: protein binding; RNA binding; structural constituent of ribosome
Biological process: cytoplasmic translation; negative regulation of myoblast fusion; spermatogenesis; striated muscle contraction; translation
Cellular component: cytoplasm; cytosol; cytosolic large ribosomal subunit; cytosolic ribosome; endoplasmic reticulum; nucleus; large ribosomal subunit; ribosome
Genetic constraint (gnomAD): Loss-of-function variants: 1 observed, 25.78 expected, observed/expected ratio (o/e) 0.0388, 90% interval 0.013 to 0.18. The upper end of that interval is the gene's LOEUF score, 0.18, which puts it in group 1 of 6, group 1 being the genes least tolerant of losing a copy. Missense variants: 134 observed, 219.65 expected, observed/expected ratio (o/e) 0.61, 90% interval 0.53 to 0.7. Synonymous variants: 74 observed, 71.92 expected, observed/expected ratio (o/e) 1.03, 90% interval 0.85 to 1.25.
Homologues: Orthologues: chimpanzee RPL17 (100% identical), tropical clawed frog rpl17 (96% identical), zebrafish rpl17 (95% identical), Drosophila melanogaster RpL17 (70% identical), Caenorhabditis elegans rpl-17 (66% identical).
Diseases named in the same sentence as RPL17 in open-access papers:
RPL17 is named in the same sentence as 36 diseases in open-access papers, as found by Europe PMC text mining. Sharing a sentence is not in itself a finding about the gene and the disease. The quoted sentences say what the papers report.
breast carcinoma (3 papers, 2020 to 2025). "Mining of these data showed that module 2 contained the bone metastasis prognosis-related gene RPL17, which is overexpressed in breast cancer-associated brain metastases." (PMID 35783639, 2022). "High Cdc20 and securin immune expression are associated with extremely poor outcomes in breast cancer patients, and overexpression of RPL17 affects breast cancer-associated brain metastases (Yuan, Wang & Cheng, 2018)." (PMID 32461838, 2020). "There are 81 key genes shared by all stages, among which RPL17, CCNB1, and SF3B4 are genes that are highly (with degrees >25) related to breast cancer." (PMID 32461838, 2020).
colorectal cancer (3 papers, 2022 to 2025). A primary or metastatic malignant neoplasm that affects the colon or rectum. "It has been reported that RPL17 could promote proliferation and stemness of colorectal cancer through ERK and NEK2/β-catenin signaling pathways." (PMID 36506302, 2022).
colon adenocarcinoma (2 papers, 2022 to 2025). "To further verify the biological importance of dysregulation of RPL17 in mediating CRC initiation and/or progression, we have also analyzed out the relationship between RPL17 overexpression and its prognostic value from TCGA-Colon adenocarcinoma big data." (PMID 35711835, 2022).
Diamond-Blackfan anemia (2 papers, 2023 to 2024). A congenital aregenerative and often macrocytic anemia with erythroblastopenia. "Analysis of two families, including a multi-generational pedigree, link Diamond-Blackfan anemia to variants of the ribosomal protein gene RPL17 and reveal unusual ribosomal RNA heterogeneity." (PMID 39088281, 2024). "The importance of critical interfaces between domains I, II and the 5.8S rRNA is further highlighted by the finding that key stabilizers of these sites include Rpl17 (RPL17 in humans) and Diamond-Blackfan anemia proteins Rpl26 (RPL26) and Rpl35 (RPL35) 24,25." (PMID 37037974, 2023).
gastric cancer (2 papers, 2016 to 2021). A primary or metastatic malignant neoplasm involving the stomach. "Moreover, RPL17 was found to be upregulated in a drug-resistant gastric cancer cell line, and overexpression of this gene conferred protection against multiple chemotherapeutic drugs in vitro." (PMID 34732136, 2021). "We therefore examined an AluYa5 pMEI that lay immediately adjacent to a proximal enhancer like element in the promoter region of RPL17, a marker of poor survival in liver cancer that may promote resistance to multiple chemotherapeutic drugs in gastric cancer." (PMID 34732136, 2021). "Among the candidates, we focused on three read‐through transcription candidates that included gastric cancer‐related genes (PHOSPHO2‐KLHL23, RPL17‐C18orf32, PRR5‐ARHGAP8)." (PMID 27833855, 2016). "We screened read‐through transcription events from stomach adenocarcinoma RNA‐seq data and selected three candidates PHOSPHO2‐KLHL23, RPL17‐C18orf32, and PRR5‐ARHGAP8, to assess their biological role in gastric cancer." (PMID 27833855, 2016).
anemia (1 paper, 2024). A reduction in the number of red blood cells, the amount of hemoglobin, and/or the volume of packed red blood cells. "Together, our data indicate that disruption of rpl17 in zebrafish alters erythropoiesis and supports a direct involvement of RPL17 mutations in anemia." (PMID 39088281, 2024). "Finally, the patients with RPL17 variants displayed other hematopoietic disorders, sometimes in parallel to anemia, including leukopenia and thrombocytopenia, which further illustrates the need to extend the definition of DBA to a broader range of conditions than pure red cell aplasia." (PMID 39088281, 2024). "Further, RPL17/uL22 depletion resulted in anemia and micrognathia in zebrafish larvae, and in vivo complementation studies indicated that RPL17 variants were pathogenic." (PMID 39088281, 2024).
asthma (1 paper, 2022). "The GSE147878 dataset further validated that genes other than RPL17 and HNRNPK were key genes regulating severe asthma." (PMID 35645813, 2022).
atherosclerosis (1 paper, 2020). A disease characterized by the build-up of fatty material and calcium deposition in the arterial wall resulting in partial or complete occlusion of the arterial lumen. "However, increased expression of RPL17 showed to inhibit the VSMC, reducing the progression of atherosclerosis, which could be a regular event that occurs in FH patients." (PMID 32760426, 2020).
Cerebral ischemia (1 paper, 2019). Restriction of arterial blood supply to the brain associated with insufficient oxygenation to support the metabolic requirements of the tissue. "By reviewing the literature, we also found that RPL17, Tuba, and Rac1 have a great relationship with the pathogenesis of cerebral ischemia and were each in one of the three more important pathways enriched by 21 DEPs." (PMID 31223330, 2019). "This validated the identification of the 21 DEPs and confirmed a role RPL17, Tuba, and Rac1 involved in three important pathways in cerebral ischemia." (PMID 31223330, 2019).
colorectal adenocarcinoma (1 paper, 2025). The most common type of colorectal carcinoma. "It was found that elevated expression of RPL31, CCT2, RPL17, and NUP85, as well as downregulation of NUP98, CDC37, DNM2, and SNRPN resulted from corresponding μ-ASOs treatment, correlating with improved survival in colorectal adenocarcinoma patients according to the TCGA database." (PMID 41373892, 2025).
colorectal tumor (1 paper, 2022). "Despite the enhanced RPL17 expression in colorectal tumor progression, the fundamental mechanisms underlying the deregulation of RPL17 remain to be defined." (PMID 35711835, 2022). "From the data investigating global gene expression in 24 human colorectal tumors against matched normal mucosa 12, we found that the average expression of RPL17 is upregulated in tumor tissues." (PMID 35711835, 2022). "Despite its altered expression in CRC tissues, the functional role of RPL17 in colorectal tumor progression has not been defined yet." (PMID 35711835, 2022). "Thus, RPL17 targeting could be the next molecular strategy for both primary CRC treatment and prevention of metastasis or recurrence in the colorectal tumor microenvironment." (PMID 35711835, 2022).
ischemic stroke (1 paper, 2019). A stroke disorder caused by obstruction of blood flow to the brain, due to thrombotic (local blood clot formation) or embolic (due to a blood clot or other material traveling from another site) event. "First of all, four proteins were involved in ribosome function during ischemic stroke, namely, RPL26, RPL17, RPL39, and RPS13." (PMID 31223330, 2019). "Whilst a role for RPL17 during ischemic has not been reported, our datasets identify this DEP as a new therapeutic target during ischemic stroke therapy." (PMID 31223330, 2019).
liver cancer (1 paper, 2021). An epithelial or non-epithelial malignant neoplasm that arises from the liver. "Using CRISPR/Cas9 deletion, we show that an RMS-derived polymorphic TE insertion increased the expression of RPL17, a gene associated with lower survival in liver cancer." (PMID 34732136, 2021). "Higher expression levels of RPL17 have been associated with reduced survival in liver cancer." (PMID 34732136, 2021).
Sepsis (1 paper, 2026). Sepsis is defined as life-threatening organ dysfunction caused by a dysregulated host response to infection. "In contrast, children with sepsis exhibited significant enrichment of genes encoding the transcriptional regulator of arginine metabolism, an uncharacterized protein, and the large subunit ribosomal protein L17." (PMID 41602763, 2026).
trisomy (1 paper, 2017). A chromosomal abnormality consisting of the presence of one chromosome in addition to the normal diploid number. "For Trisomy 18, investigators can examine the ribosomal protein gene (RPL17), located at chromosome 18q21.1-q21.1; however, the association between RPL17 and Trisomy 18 detection has yet to be investigated." (PMID 28717645, 2017).
tuberculous pleurisy (1 paper, 2021). "It is possible that there is also an extra-ribosomal mechanism of RPL17 in tuberculous pleurisy, which requires further studies to confirm." (PMID 34925441, 2021). "In summary, by integrating WGCNA with differential gene expression analysis, our study generated the significant gene RPL17 that has potential for diagnosis and treatment in tuberculous pleurisy." (PMID 34925441, 2021). "In the end, RPL17 was identified as a gene that can be the biomarker of tuberculous pleurisy." (PMID 34925441, 2021). "Finally, we determined that RPL17 may be a biomarker of tuberculous pleurisy." (PMID 34925441, 2021).
tumor (9 papers, 2016 to 2022). "On day 23, a significant difference was evident in the tumor size and weight of the control and RPL17 knockdown group." (PMID 35711835, 2022). "Nine days after the inoculation, there was a clear difference in tumor sizes between the control and RPL17 knockdown, such that the tumor sizes of the control were larger." (PMID 35711835, 2022). "Additionally, a mouse xenograft model showed that targeting RPL17 significantly inhibited tumor growth." (PMID 35711835, 2022). "We next sought to find a molecular explanation of how RPL17 functions in tumor progression." (PMID 35711835, 2022). "Similarly, targeting RPL17 effectively suppressed tumor formation in a mouse xenograft model." (PMID 35711835, 2022). "If the expression of RPL17 is down-regulated, it will lead to VSMC proliferation; RPL17 has a tumor suppressor effect." (PMID 35459093, 2022). "Importantly, ribosome pathway factors were recently reported to mediate the formation of the carotid intima in mice in response to injury, and ribosomal protein L17 (RPL17), similar to tumor suppressors, can inhibit VSMC cell cycle progression." (PMID 27275925, 2016).
infection (2 papers, 2024 to 2025). The state of being infected such as from the introduction of a foreign agent such as serum, vaccine, antigenic substance or organism. "CFU calculation suggested intracellular Brucella of TBC1D3F- and Rpl17-C18orf32-null cells increased at 2.5 days, 4.5 days, and 7 days post infection." (PMID 38376367, 2024).
RPL17 also shares sentences with these, for which no sentence is quoted: cancer (3 papers); cardiovascular disease (2); Cognitive impairment (2); bladder cancer (1); co-infection (1); depression (1); diabetes (1); glaucoma (1); leukopenia (1); Micrognathia (1); myocardial infarction (1); prostate carcinoma (1); red cell aplasia (1); retinitis pigmentosa (1); schizophrenia (1); stomach adenocarcinoma (1); Stroke (1); Thrombocytopenia (1).